BIRC5 (baculoviral IAP repeat containing 5)
Diseases named in the same sentence as BIRC5 in open-access papers (continued):
Sharing a sentence is not in itself a finding about the gene and the disease.
serous ovarian cancer (3 papers, 2011 to 2021). "Remarkably, higher expression of BIRC5 was associated with better OS in the advanced stages of serous ovarian cancer." (PMID 34577856, 2021). "All these data suggest that BIRC5 is highly expressed in high grade serous ovarian cancer and the level of survivin overexpression is associated with poor prognosis." (PMID 29212257, 2017). "In absence of additional supporting evidence, it is not possible to conclude that dysregulation of BIRC5 and NBEA affects the prognosis of serous ovarian cancer." (PMID 34577856, 2021).
thymoma (3 papers, 2013 to 2022). A neoplasm arising from the epithelial cells of the thymus. "Deep deletions were more common in thymoma (THYM), but only 3/123 cases harbored genetic alterations in BIRC5 (2 cases with deep deletions and 1 case with DNA amplification)." (PMID 35331169, 2022).
thyroid cancer (3 papers, 2014 to 2022). "The results of the study showed that survivin gene BIRC5 was expressed at significantly higher levels in the thyroid cancers (P = 0,0232), than in benign thyroid nodules." (PMID 24945990, 2014).
viral infection (3 papers, 2019 to 2024). "In contrast, the expression of control BIRC5 transcript, which was not altered by miR-7-5p in vitro, was not inhibited in vivo and instead was increased during in vivo virus infection." (PMID 31363027, 2019).
acute leukemia (2 papers, 2016 to 2022). A clonal (malignant) hematopoietic disorder with an acute onset, affecting the bone marrow and the peripheral blood. "The candidate targets of Wilms tumor 1 (WT1), survivin (BIRC5), and PRAME were selected given the high prevalence in relapsed and refractory acute leukemias (77-81% for WT1, 63-100% for BIRC5, and 42-87% for PRAME)." (PMID 36248870, 2022). "In patients with active acute leukemia after HCT (MRD+ or relapse; n=19), the blood levels of WT1/ABL1, PRAME/ABL1, and BIRC5/ABL1 exceeded healthy donors (p<0.0001, p=0.0286, and p=0.0064 respectively)." (PMID 36248870, 2022). "To date, WT1, BIRC5, and PRAME have not been promoted as biomarkers of relapse, likely in part due to the scant data for BIRC5 and PRAME and the lack of sensitivity for detection of relapse in prior studies of WT1 in acute leukemia." (PMID 36248870, 2022).
adenoma (2 papers, 2014 to 2024). A neoplasm arising from the epithelium. "Impaired apoptosis, an essential feature of early adenomatous growth, might also be related to the increased expression of BIRC5 we documented in our adenomas." (PMID 24472434, 2014).
adrenocortical carcinoma (2 papers, 2022 to 2023). "The highest HR values for OS and BIRC5 expression were found for adrenocortical carcinoma (ACC) and pheochromocytoma and paraganglioma (PCPG), both of which are hormone-producing tumors." (PMID 35331169, 2022).
Arthritis (2 papers, 2022 to 2024). Inflammation of a joint. "Concomitantly with the shrinkage of the stably present SLSFs, we observed the emergence of arthritis-specific Thy1+ SF subpopulations (Dkk3/Lrrc15+ and Birc5/Aqp1+), accompanied by expansion of Prg4high/Thy1-LSFs." (PMID 35879783, 2022).
atherosclerosis (2 papers, 2019 to 2025). A disease characterized by the build-up of fatty material and calcium deposition in the arterial wall resulting in partial or complete occlusion of the arterial lumen. "Thus, we inferred that NONMMUT002434 promote atherosclerosis by inhibiting IL10 and BIRC5, thus promoting inflammation and cell apoptosis." (PMID 30850398, 2019).
cutaneous melanoma (2 papers, 2021 to 2022). A primary melanoma arising from atypical melanocytes in the skin. "Survivin, a protein encoded by the E2F target gene BIRC5, has been suggested as a prognostic marker in several canine tumors, including cutaneous melanoma." (PMID 34485433, 2021).
endometrioid adenocarcinoma (2 papers, 2017 to 2022). An adenocarcinoma characterized by the presence of malignant glandular epithelial cells resembling endometrial cells. "The expression of BIRC5 increased sequentially from proliferative endometrium to endometrial hyperplasia to endometrioid adenocarcinoma." (PMID 35672846, 2022).
endometriosis (2 papers, 2020 to 2022). The growth of functional endometrial tissue in anatomic sites outside the uterine body. "In humans, BIRC3 and BIRC5 are expressed in the endometrium, and aberrant expression of these IAPs is associated to endometriosis and endometrial cancer." (PMID 34530503, 2022). "Increased expression of BIRC2, BIRC3, BIRC4, and BIRC5 is associated with endometriosis, and tumor necrosis factor-α increases BIRC3 expression in endometrial stromal cells in vitro." (PMID 34530503, 2022). "In our study, the expression of BIRC5 in the peripheral blood of women with endometriosis showed an accuracy of 88.7%, with a sensitivity of 97.2% and specificity of 65.5%." (PMID 32751449, 2020). "The accuracy of BIRC5 expression in the peripheral blood for the diagnosis endometriosis presented AUC of 0.887 (p < 0.001), with 97.2% of sensitivity and specificity of 65.5% considering the overall endometriosis group." (PMID 32751449, 2020). "The BIRC5 expression was also significantly higher in women with endometriosis, regardless of the endometriosis stage (minimal/mild and moderate/severe endometriosis)." (PMID 32751449, 2020). "The data suggest that BIRC5 expression may be a potential minimally invasive biomarker in the diagnosis of endometriosis." (PMID 32751449, 2020). "In conclusion, increased expression of the BIRC5 gene in the peripheral blood of women with endometriosis may indicate their role in cell proliferation and anti-apoptotic activity in the development of the disease." (PMID 32751449, 2020). "The findings suggest that the expression of BIRC5 may be a potential noninvasive biomarker for the diagnosis of endometriosis." (PMID 32751449, 2020). "The BIRC5 expression was significantly higher in all phases of the menstrual cycle in women with endometriosis, regardless of the disease stage." (PMID 32751449, 2020). "Our results showed that BIRC5 is differently expressed in women with endometriosis compared with healthy controls, regardless of the endometriosis stage." (PMID 32751449, 2020). "In the current study, the expression pattern of BIRC5 as a potential non-invasive biomarker was assessed in the peripheral blood samples taken during different phases of the menstrual cycle of women with and without endometriosis." (PMID 32751449, 2020). "Therefore, we aimed to evaluate the expression of BIRC5 in samples of peripheral blood of women with and without endometriosis." (PMID 32751449, 2020). "Therefore, the aim of the present study was to evaluate the expression of BIRC5 in samples of peripheral blood of women with and without endometriosis." (PMID 32751449, 2020).
esophageal tumor (2 papers, 2019 to 2021). "Targeting BIRC5 may be a promising strategy against esophageal tumor relapse and chemoradioresistance." (PMID 31093306, 2019). "The stage-based assessment of overexpressed genes showed significant overexpression of BIRC5, APOC2, CENPF, STMN1, and HNRPC across all cancer stages including early, locally advanced and metastatic esophageal tumors." (PMID 33828156, 2021).
head and neck cancer (2 papers, 2021 to 2022). A primary or metastatic malignant neoplasm affecting the head and neck. "For instance, patients with head and neck cancer may respond more favorably to therapy if the nuclear export signal for BIRC5 is deactivated." (PMID 36358602, 2022). "In addition to Bcl-2, increased levels of members of the inhibitors of apoptosis (IAP) family including BIRC2, BIRC3, BIRC5/survivin, and XIAP are associated with cisplatin resistance and worse clinical outcome in patients of ovarian, esophageal, or head and neck cancer." (PMID 34645978, 2021).
head and neck squamous cell carcinoma (2 papers, 2020 to 2023). A squamous cell carcinoma that arises from any of the following anatomic sites: lip and oral cavity, nasal cavity, paranasal sinuses, pharynx, larynx, and salivary glands. "A literature search found only nine studies analyzing BIRC5 polymorphisms in head and neck squamous cell carcinomas." (PMID 38139318, 2023). "This study identified a total of 18 polymorphisms in the BIRC5 gene, 11 of which had a minor allele frequency (MAF) of more than 5% in head and neck squamous cell carcinoma (HNSCC) patients in Croatia." (PMID 38139318, 2023).
Hepatic fibrosis (2 papers, 2023 to 2025). The presence of excessive fibrous connective tissue in the liver. "BIRC5 is associated with early activation of hepatic astrocytes and the development of hepatic fibrosis." (PMID 37035748, 2023). "The expression of BIRC5 is related to the activation of HSCs, which may promote the occurrence of liver fibrosis." (PMID 40725496, 2025).
HIV-1 infection (2 papers, 2015 to 2021). The type species of lentivirus and the etiologic agent of acquired immunodeficiency syndrome (AIDS). "BIRC5 inhibits apoptosis, and its downregulation in both early and late HIV-1 infection could contribute to HIV-associated depletion of T-cells." (PMID 26426037, 2015). "DDX3 inhibition also resulted in the downregulation of BIRC5, critical to cell survival during HIV-1 infection, and selectively induced apoptosis in viral RNA-expressing CD4+ T cells but not bystander cells." (PMID 33931637, 2021).
human papillomavirus infection (2 papers, 2022 to 2023).
intrahepatic cholangiocarcinoma (2 papers, 2016 to 2020). A carcinoma that arises from the intrahepatic bile duct epithelium in any site of the intrahepatic biliary tree. "BIRC5 was upregulated in intrahepatic cholangiocarcinoma, and may contribute to the development of diagnostic and therapeutic strategies." (PMID 32040444, 2020).
ovarian serous carcinoma (2 papers, 2017 to 2021). "BIRC5 was highly expressed in high grade serous ovarian carcinoma compared with ovarian, fallopian tube epithelia, and peritoneal fluid based on a large number of cancer patients from three different databases and current study." (PMID 29212257, 2017).
pancreatic ductal adenocarcinoma (2 papers, 2019 to 2022). An infiltrating adenocarcinoma that arises from the epithelial cells of the pancreas. "Birc5 is expressed during embryonic development and cannot be detected in most terminally differentiated tissues, and it is also highly expressed in many tumors such as pancreatic ductal adenocarcinoma." (PMID 31791390, 2019).
prostate adenocarcinoma (2 papers, 2020 to 2022). "To explore the clinical relevance of YAP targeting in PCa we generated a signature of four genes induced by YAP (CTGF, CYR61, BIRC5 and ANRDK1) and interrogated the prostate adenocarcinoma Cancer Genome Atlas (TCGA)." (PMID 33032653, 2020). "Similarly, in our study, by differential expression analysis from prostate adenocarcinoma TCGA database, we demonstrated that all the principal YAP transcriptional targets, CTGF, CYR61, BIRC5 and ANRDK1, were highly enriched in the patients with PCa tumors, compared with tumor free patients." (PMID 33032653, 2020).
soft tissue sarcoma (2 papers, 2022 to 2023). A malignant neoplasm arising from muscle tissue, adipose tissue, blood vessels, fibrous tissue, or other supportive tissues excluding the bones. "In soft tissue sarcoma, a signature consisting of SECTM1 and other four immune-related genes, IFIH1, CTSG, STC2, and BIRC5, could predict prognosis and the responses to ICIs23 These evidence further enhanced the correlation of SECTM1 with anti-tumor immunity." (PMID 36818292, 2023).
synovial sarcoma (2 papers, 2019 to 2024). "We observed a 39.5% reduction in normalized BIRC5 expression in YM155 treated synovial sarcomas (p = 0.0006)." (PMID 30909651, 2019). "The decrease in Birc5 and survivin expression, the induction of apoptosis, and the decrease in cell viability were clearly detected in synovial sarcoma upon YM155 exposure." (PMID 30909651, 2019). "We have demonstrated that histone modifications are altered in synovial sarcoma cells at the Birc5 promoter upon YM155 administration." (PMID 30909651, 2019). "The direct target of YM155 remains unproven, but the effects on epigenetic changes at the Birc5 promoter are evident in synovial sarcoma." (PMID 30909651, 2019). "These means in synovial sarcoma represent a log2 ratio of 5.3 or about a 40-fold increase in Birc5 expression over mouse skeletal muscle." (PMID 30909651, 2019). "Using the web-based data inquiry tool Metabolic gEne RApid Visualizer (MERAV), we searched human cancers that have been previously targeted in clinical trials using YM155 and compared the BIRC5 gene expression levels in these cancers to synovial sarcoma." (PMID 30909651, 2019). "Using the HS-SY-II human synovial sarcoma cell line, we sought to delineate the epigenetic mechanisms surrounding the BIRC5 promoter in response to 0.2 μM YM155 after 24 h of treatment." (PMID 30909651, 2019). "The ratio between Birc5 expression in the mouse synovial sarcomas compared to the normal tissue was 7.0 and was very comparable to the 6-fold increase seen in the human comparison." (PMID 30909651, 2019). "Because YM155 is an effective pro-apoptotic compound, it has been difficult to determine if survivin expression is a direct effect of the drug on epigenetic regulation of the Birc5 promoter or if it is a secondary consequence of activating other pro-apoptotic pathways in synovial sarcoma." (PMID 30909651, 2019). "Investigations into the molecular mechanisms underpinning FAM83D’s regulation of STAT1, BIRC5, MCM2, as well as CDK1 in synovial sarcoma, are currently underway in our laboratory." (PMID 38512482, 2024). "Collectively, these results point to a potential involvement for FAM83D in the development of synovial sarcoma could be mediated via the regulation of STAT1, BIRC5, MCM2, as well as CDK1." (PMID 38512482, 2024). "We observed that synovial sarcoma was not dissimilar from other cancers in terms of their BIRC5 gene expression nor in the ratio of gene expression found in the cancer compared to the corresponding normal tissue." (PMID 30909651, 2019).
abortion (1 paper, 2022). the ending of pregnancy by removing a fetus or embryo before it can survive outside the uterus. "In abortion-prone mice, increased placental BIRC5 expression during early pregnancy is associated with pregnancy loss, although the role of BIRC5 in pregnancy failure is not fully understood." (PMID 34530503, 2022).
acne (1 paper, 2023). An inflammatory process of the sebaceous glands which is characterized by comedones, nodules, papules and/or pustules on the skin.
asthma (1 paper, 2023). "Accumulating evidence shows that ITGB4, SEMA3D, FCAR (Fc fragment of IgA receptor), KIT (KIT proto-oncogene, receptor tyrosine kinase), PGLYRP1, IL17RB, BIRC5 and PTGS1 are associated with prognosis in asthma." (PMID 36837510, 2023).
autosomal dominant polycystic kidney disease (1 paper, 2021). Autosomal dominant form of polycystic kidney disease. "Birc5 (also known as Survivin) has been implicated in a number of kidney conditions, including autosomal-dominant polycystic kidney disease, acute kidney injury and renal cell carcinomas, however its role in context of normal kidney development is still unknown." (PMID 34789782, 2021).
B-cell acute lymphocytic leukaemia (1 paper, 2021). "We have previously shown that BIRC5 was associated with different 11q23/MLL abnormalities in adults with B-cell acute lymphocytic leukaemia and in this study elevated BIRC5 expression was found in adult AML patients with complex cytogenetic abnormalities." (PMID 34638823, 2021).
basal cell carcinoma (1 paper, 2025). A carcinoma involving the basal cells. "Intriguingly, survivin/Birc5 expression has been shown to be critical for both hES cell generation of teratomas and oncogene targeted stem cell initiation of basal cell carcinoma." (PMID 40361430, 2025).
benign adrenocortical adenomas (1 paper, 2022). "Upregulation of BIRC5 was reported in ACC compared to benign adrenocortical adenomas and normal adrenal glands, and the upregulation may associate with poor ACC prognosis (p = 0.053)." (PMID 35681785, 2022).
benign schwannomas (1 paper, 2008). "BIRC5 is located within a 2 Mb region in 17q25 previously shown to be commonly amplified in MPNSTs, and increased expression of BIRC5 in MPNSTs compared to neurofibromas and benign schwannomas has been reported." (PMID 18522746, 2008).
bladder tumor (1 paper, 2017). "BIRC5 plays a crucial role in cell proliferation, adjusting the cell survival time, inhibiting the role of apoptosis, inhibiting the expression of the downstream product of BIRC5, and promoting cancer cell apoptosis in bladder tumor." (PMID 29190974, 2017).
carcinoid (1 paper, 2020). "Radiation exposure increased BIRC5 gene expression in a human carcinoid cell line." (PMID 32577168, 2020).
chondrosarcoma (1 paper, 2016). A malignant cartilaginous matrix-producing mesenchymal neoplasm arising from the bone and soft tissue. "siRNA screening for 51 apoptosis-related genes in JJ012 chondrosarcoma cells identified BIRC5, encoding survivin, as essential for chondrosarcoma survival." (PMID 27159675, 2016).
conjunctival melanoma (1 paper, 2021). "Moreover, Ocoxin downregulated the apoptotic inhibitor BIRC5, which was previously found to be upregulated in uveal and conjunctival melanoma." (PMID 33669949, 2021).
coronary artery diseases (1 paper, 2021). "Among hypoxia-responsive genes identified in our in vitro hypoxic system, we also found potential cardiac biomarkers (BIRC5, ENG, HMOX1, VEGF, STC1, STC2, and SERPINE1) which they may have potential clinical value in the diagnosis and prognosis of coronary artery diseases." (PMID 34685725, 2021).
depression (1 paper, 2022). "Moreover, the ITM aggravated PC progression which was attenuated by BIRC5 depression." (PMID 35461228, 2022).
embryonal carcinoma (1 paper, 2021). A non-seminomatous malignant germ cell tumor characterized by the presence of large germ cells with abundant cytoplasm resembling epithelial cells, geographic necrosis, high mitotic activity, and pseudoglandular and pseudopapillary structures formation. "Our stemness analysis validated the role of BIRC5 in the development and maintenance of embryonic stem cells and embryonal carcinomas." (PMID 34685742, 2021). "In this analysis, BIRC5 and EOMES were found to overlap in embryonic stem cells and embryonal carcinoma." (PMID 34685742, 2021).
esophageal adenocarcinoma (1 paper, 2025). A malignant tumor with glandular differentiation arising predominantly from Barrett mucosa in the lower third of the esophagus. "Interestingly, BIRC5 has been shown to be overexpressed in esophageal adenocarcinoma and is one of the autophagy-related genes, which may serve as a biomarker for the diagnosis and prognosis of esophageal adenocarcinoma." (PMID 39944135, 2025).
gastrointestinal NETs (1 paper, 2023). "It has been reported that BIRC5 is commonly overexpressed in gastrointestinal NETs and other cancer types, and overexpression has been related to low radiosensitivity and worse prognosis." (PMID 37076494, 2023).
gastrointestinal stromal tumor (1 paper, 2021). "Here we review some of the most relevant evidences about the role of BIRC5 emerged in hepatocellular carcinomas, gastrointestinal stromal tumors, prostate tumors and tumors of the nervous system." (PMID 33413657, 2021).